UBAC2 (UBA domain containing 2)
Description:
Acts as an ER-phagy receptor required for the selective autophagic degradation of endoplasmic reticulum (ER) fragments to maintain ER homeostasis and restrain ER stress-induced inflammatory responses. Its function depends on phosphorylation-induced dimerization, which enhances interaction with GABARAP and facilitates recruitment of ER fragments to autophagosomes. Restricts trafficking of FAF2 from the endoplasmic reticulum to lipid droplets. In association with LMBR1L and E3 ubiquitin-protein ligase AMFR, negatively regulates the canonical Wnt signaling pathway in the lymphocytes by promoting the ubiquitin-mediated degradation of CTNNB1 and Wnt receptors FZD6 and LRP6.
Synonyms: PHGDHL1; FLJ30548; RP11-178C10.1
Tractability: Antibody: UniProt predicts a signal peptide or a membrane-spanning region. PROTAC: ubiquitination databases record sites on it; its protein half-life has been measured.
Gene: Protein-coding gene on chromosome 13 (99,200,758 to 99,386,504, forward strand). Ensembl gene ENSG00000134882.
Subcellular location: Endoplasmic reticulum membrane
Subcellular location (Human Protein Atlas): Cytosol
Gene Ontology:
Molecular function: protein binding; serine-type endopeptidase activity
Biological process: negative regulation of canonical Wnt signaling pathway; negative regulation of inflammatory response; negative regulation of retrograde protein transport, ER to cytosol; protein localization to endoplasmic reticulum; reticulophagy
Cellular component: endoplasmic reticulum; endoplasmic reticulum membrane
Genetic constraint (gnomAD): Loss-of-function variants: 21 observed, 35.2 expected, observed/expected ratio (o/e) 0.6, 90% interval 0.42 to 0.86. The upper end of that interval is the gene's LOEUF score, 0.86, which puts it in group 3 of 6, group 1 being the genes least tolerant of losing a copy. Missense variants: 272 observed, 365.16 expected, observed/expected ratio (o/e) 0.74, 90% interval 0.67 to 0.82. Synonymous variants: 139 observed, 141.05 expected, observed/expected ratio (o/e) 0.99, 90% interval 0.86 to 1.13.
Homologues: Orthologues: chimpanzee UBAC2 (100% identical), macaque UBAC2 (98% identical), guinea pig UBAC2 (93% identical), dog UBAC2 (90% identical), mouse Ubac2 (89% identical), rat Ubac2 (87% identical), pig UBAC2 (87% identical), tropical clawed frog ubac2 (66% identical), zebrafish ubac2 (64% identical), Drosophila melanogaster rngo (15% identical), Caenorhabditis elegans ddi-1 (9% identical). Paralogues in human: DDI2 (17% identical), DDI1 (14% identical), NRIP2 (11% identical), NRIP3 (10% identical).
Diseases named in the same sentence as UBAC2 in open-access papers:
UBAC2 is named in the same sentence as 15 diseases in open-access papers, as found by Europe PMC text mining. Sharing a sentence is not in itself a finding about the gene and the disease. The quoted sentences say what the papers report.
Behçet's disease (6 papers, 2009 to 2024). "Since UBAC2 is a high frequency mutation gene associated with Behcet’s disease, skin, and bladder cancer, the immune dysregulation associated with ER-phagy can be a promising therapy target for further clinical diagnosis and treatment." (PMID 39284914, 2024). "UBAC2 is a risk allele of Behcet’s disease and the enhanced UBAC2 expression prompts the progress of Behcet’s disease." (PMID 39284914, 2024). "It was reported that the polymorphism of UBAC2 gene was related to Behcet’s disease and UBAC2 gene was the risk allele of Behcet’s disease." (PMID 32913183, 2020). "In this study we performed a candidate gene analysis combined with a fine mapping study and the result showed a link of several SNPs in the UBAC2 gene with the susceptibility to Behçet's disease in Chinese Han patients." (PMID 22455605, 2012). "Fine mapping and validation studies further confirmed UBAC2 as susceptibility gene for Behçet's disease." (PMID 22455605, 2012). "These genetic associations and functional studies suggest that UBAC2 is a risk gene for Behçet's disease." (PMID 22455605, 2012). "No information on polymorphism of the UBAC2 gene in pigs is available in the literature; however, based on the association of the gene with Behcet’s disease and its manifestation in humans, the UBAC2 gene is a promising candidate for further investigation of congenital anomalies in pigs." (PMID 34327051, 2021). "Previous reports have revealed that functional variants within the UBAC2 genes are related to the increased risk of inflammatory diseases, including Behcet’s disease, non-melanoma skin cancer, and Alzheimer’s disease." (PMID 39284914, 2024). "The SNPs rs9513584 and rs4936742 located within the genes UBAC2 (ubiquitin-associated domain [UBA] containing 2) and UBASH3B (ubiquitin associated and SH3 domain containing, B) were also associated with Behçet's disease with P values of 5.8 × 10-3 and 1.5 × 10-3, respectively." (PMID 19442274, 2009). "Two other GWAS did not identify the UBAC2 gene as the risk gene for Behçet's disease." (PMID 22455605, 2012). "However, the association between rs9513584 within UBAC2 and Behçet's disease is not significant after correction for multiple testing." (PMID 19442274, 2009).
bladder cancer (2 papers, 2020 to 2024). "UBAC2 has also been reported to be highly correlated with the development of malignant tumors (including skin and bladder cancer) and inflammatory bowel diseases." (PMID 39284914, 2024). "However, the functions and underlying molecular mechanisms of UBAC2 in bladder cancer (BC) development have not been defined." (PMID 32913183, 2020).
colitis (1 paper, 2024). Inflammation of the colon. "In mice expressing disease-associated human UBAC2 mutants, the ER-phagy was decreased, while the inflammatory responses and DSS-induced colitis was incensed." (PMID 39284914, 2024).
myocardial infarction (1 paper, 2023). Gross necrosis of the myocardium, as a result of interruption of the blood supply to the area, as in coronary thrombosis. "Regarding myocardial infarction, a study of high-throughput RNA sequencing found that 3,862 circRNAs are dysregulated in peripheral blood, and the differentially expressed circ-TMEM165, circ-UBAC2, circ-ZNF609, circ-ANKRD12, and circ-SLC8A1 are confirmed in the AC16 cell model." (PMID 37840751, 2023).
Papillary thyroid carcinoma (1 paper, 2021). "For example, the DNA methylation patterns of UBAC2 and ELOVL2, which are highly correlated with Chromosomal instability, provide potential prognostic value in Papillary thyroid carcinoma." (PMID 33550277, 2021).
ulcerative colitis (1 paper, 2024). An inflammatory bowel disease involving the mucosal surface of the large intestine and rectum. "Moreover, by affecting ER-phagy, UBAC2 restrains inflammatory responses and acute ulcerative colitis (UC) in mice." (PMID 39284914, 2024). "UBAC2 variants from inflammatory diseases or point mutation in the LIR motif of UBAC2 decrease ER-phagy flux and increase sterile inflammation associated with ER stress in vivo, which makes mice more susceptible to dextran sulfate sodium (DSS)-induced ulcerative colitis (UC)." (PMID 39284914, 2024). "Phosphorylation-induced UBAC2 dimerization facilitates binding to autophagosomal GABARAP and restrains acute ulcerative colitis via ER-phagy." (PMID 39284914, 2024).
urothelial carcinoma (1 paper, 2020). A malignant neoplasm derived from the transitional epithelium of the urinary tract (urinary bladder, ureter, urethra, or renal pelvis). "In order to evaluate the expression level of UBAC2 in BC, we analyzed 48 pairs of urothelial carcinoma of bladder tissues and surrounding normal bladder tissues by qRT-PCR assay." (PMID 32913183, 2020).
malignant tumors (2 papers, 2020 to 2022). "UBAC2, which serves as a regulator of ER-associated protein degradation, plays a critical role in promoting the occurrence and development of malignant tumors." (PMID 36059957, 2022). "Recently, a growing body of evidences demonstrated that UBAC2 was also closely related to the occurrence and development of malignant tumors, such as skin cancer and BC12,13." (PMID 32913183, 2020). "Emerging evidences have demonstrated that ubiquitin-associated domain-containing protein 2 (UBAC2) is closely related to the occurrence and development of malignant tumors." (PMID 32913183, 2020).
tumor (2 papers, 2021 to 2024). "According to the correlation between the predictive expression of 7 metastasis-related lncRNAs and the OS of ccRCC patients from TCGA database, the expression of SSR3-6, WISP1-2, CYP4F22-3 and UBAC2-6 were identified in carcinoma and adjacent tissues of ccRCC patients (normal=9, tumor=9)." (PMID 34150667, 2021).
UBAC2 also shares sentences with these, for which no sentence is quoted: Alzheimer disease (1 paper); atherosclerosis (1); carcinoma (1); metastasis (1); non-melanoma skin carcinoma (1); uveitis (1).